APOB (apolipoprotein B)
Diseases named in the same sentence as APOB in open-access papers (continued):
Sharing a sentence is not in itself a finding about the gene and the disease.
atherosclerosis (continued). "For the first time, we reported an underlying shared link between two atherosclerosis factors (SUA and apoB) and nutrients, as well as their joint adverse impact on all-cause and cause-specific mortality." (PMID 31581458, 2019). "Apolipoprotein B is a low-density lipoprotein involved in the progression of atherosclerosis by reducing nitric oxide-dependent relaxation of artery walls." (PMID 31434198, 2019). "Mutations in the human APOB gene cause familial hypercholesterolemia that is characterized by pathogenic elevated LDL-cholesterol levels and atherosclerosis (e.g.68)." (PMID 31065004, 2019). "The expression of the APOB gene is positively correlated with the degree of atherosclerosis, and the composition and function of platelets in patients with hyperlipidemia is altered." (PMID 31212963, 2019). "Previously, we generated transgenic mice overexpressing the human APOB-100 protein, a mouse model of human atherosclerosis." (PMID 30410436, 2018). "The transendothelial transport of apoB-lipoproteins plays a pivotal role in the pathogenesis of atherosclerosis." (PMID 30320124, 2018). "In summary, the present study has revealed that bLF can decrease serum Hcy, leptin and several traditional risk factors, which are connected with atherosclerosis development such as TC, TG, LDL-C and ApoB in rats fed with high-cholesterol diet." (PMID 30680078, 2018). "The experimental setup described in this paper was designed as a substudy to one testing the effects of a human antibody against oxidized apolipoprotein B on atherosclerosis." (PMID 29682581, 2018). "These doubly deficient mice exhibit high levels of apoB-100-LDL-C, more closely mirroring the plasma lipid profiles in human Type II FH, and slowly and progressively present with severe spontaneous atherosclerosis on a normal chow diet." (PMID 29977908, 2018). "In previous studies, we found that the apoB gene was associated with IMT, LDL level, and ABI, which is involved in atherosclerosis and CAS." (PMID 29514644, 2018). "Hyperhomocysteinemia has also been shown to enhance the production of cholesterol and promote the secretion of ApoB, and thus worsen atherosclerosis." (PMID 29245986, 2017). "To date, as part of LDL, elevated serum apoB levels, especially the apoB/apoA ratio, were previously reported to contribute to atherosclerosis." (PMID 29018401, 2017). "Although ApoB is pivotal for lipid absorption and triglyceride homeostasis, high levels in the plasma can induce atherosclerosis." (PMID 29245986, 2017). "SdLDL apoB is a LDL subtype closely associated with diabetes and atherosclerosis, because of its greater susceptibility to undergo oxidative modification and glycation compared with more buoyant LDL." (PMID 29187850, 2017). "In the ensuing decades, we learned that the key sources of cholesterol in the pathogenesis of atherosclerosis are apolipoprotein B (apoB)-lipoproteins from plasma." (PMID 28299190, 2017). "In this context, a similar differential effect of dose on atherosclerosis was reported for a peptide derived from apolipoprotein B-100 called P6." (PMID 29091929, 2017). "The ApoB level is predictive for atherosclerosis, and the onset of obesity is usually accompanied by overproduction of ApoB." (PMID 29157198, 2017). "Several Studies have shown the protection against atherosclerosis by modulating the immune system using ApoB and HSP60 peptides in early stages of the disease but a curative effect of immune modulation has not been studied so far11–18." (PMID 28638138, 2017). "Atherosclerosis is characterized by excess accumulation of cholesterol-rich, apolipoprotein B (apoB)-containing lipoprotein in the subendothelial space (intima) of susceptible areas of arteries, which in turn triggers chronic inflammatory responses." (PMID 28790455, 2017).
atherosclerosis (continued). "Large differences in apoB, apoCI, apoCIII,apoF, apoH, and LPa between CKD5 and CVD patients were found, underlining the factthat atherosclerosis in patients with CKD is a different process than that inpatients with classical CVD." (PMID 27600335, 2016). "From the pathophysiological aspect, atherosclerosis initiates from disrupted endothelium which allows circulating apolipoprotein B (apoB)-containing lipoproteins to penetrate and accumulate in subendothelium where they further undergo chemical modification." (PMID 27447612, 2016). "Deposition of ApoB within the arterial wall, which is one of the initiating steps of atherosclerosis, was detected in coronary plaques by fluorescent microscopy." (PMID 27004558, 2016). "Atherosclerosis represents a failure to resolve the inflammatory response in the arterial wall initiated by the retention of apolipoprotein B (apoB)-containing lipoproteins." (PMID 25429291, 2014). "ApoB/apoA1 ratio has also been shown to be a good predictor of cardiovascular disease and atherosclerosis, and it has been suggested that ApoB/apoA1 ratio should be used instead of cholesterol concentrations as a risk marker of myocardial infarction." (PMID 25000408, 2014). "At the core of most cardiovascular events is atherosclerosis, a chronic inflammatory condition of the macrovasculature initiated by the subendothelial retention of apolipoprotein B (apoB)-containing lipoproteins." (PMID 25517033, 2014). "Several studies have demonstrated effective early reduction of atherosclerosis in hyperlipidemic mouse models by inducing tolerance to modified lipids and peptides derived from apolipoprotein B (ApoB) 100, HSPs 60/65, and β2-glycoprotein." (PMID 23505495, 2013). "ApoB protein plays a crucial role in atherosclerosis as immunization with some peptides derived from ApoB protein reduce atherosclerotic lesion in several mouse models." (PMID 24349031, 2013). "Plasma apoA1 and apoB levels are stronger predictors of premature atherosclerosis than other plasma lipoproteins." (PMID 22811893, 2012). "Passive administration of recombinant human antibodies against aldehyde-modified apolipoprotein B-100 peptide sequences was observed to inhibit atherosclerosis in ApoE−/− mice." (PMID 22957222, 2012). "Apolipoproteins such as ApoB are known as significant predictors of development atherosclerosis and even better than lipid profile." (PMID 20109192, 2010). "Deletion of MCP-1 in low-density lipoprotein receptor-null mice and mice expressing human apolipoprotein B attenuated the progression of dietary-induced atherosclerosis." (PMID 17450221, 2007). "The pathophysiology of atherosclerosis has evolved from the cholesterol-centric model to the response-to-retention hypothesis, highlighting the role of apolipoprotein B (ApoB)-containing lipoproteins in initiating vascular inflammation and plaque formation." (PMID 42078291, 2026). "Second, ApoB mutations or serum levels are associated with features of cognitive impairment that are not readily connected to atherosclerosis." (PMID 41099152, 2026). "KD of these TFs decreases plasma apoB-Lps, lipogenesis, and atherosclerosis, without causing hepatosteatosis or increasing plasma AST/ALT in mice." (PMID 39782688, 2025). "Consequently, elevated apoB levels not only reflect an increased atherogenic burden but also play a direct mechanistic role in the initiation and progression of atherosclerosis." (PMID 41374382, 2025). "Atherogenic index of plasma (AIP), a recognized marker for assessing atherosclerosis risk, demonstrated a positive correlation with HbA1c levels, while low‐density lipoprotein cholesterol (LDL‐C) and apolipoprotein B (APOB) also increased in tandem with HbA1c levels." (PMID 40492515, 2025).
atherosclerosis (continued). "The progression of atherosclerosis has been linked to the high concentration of ox-LDL and ApoB." (PMID 39944697, 2025). "However, recent advances based on peptide-specific tetramer staining and single-cell transcriptomics have identified CD4+ T cells reactive to native ApoB in murine and human atherosclerosis, challenging the exclusivity of modified ApoB in this process." (PMID 40552286, 2025). "Meanwhile, ApoB plays a key role in promoting atherosclerosis." (PMID 40140819, 2025). "Moreover, the rabbit model was more similar to developing human atherosclerosis when considering the expression change of APOA4 and APOB, thus making the rabbit a more suitable animal model to investigate human atherosclerosis." (PMID 39364866, 2025). "Furthermore, some studies have suggested that the ApoB–apolipoprotein A1 (ApoA1) ratio has a higher predictive value for atherosclerosis and intima-media thickness than individual lipid markers." (PMID 39851250, 2025). "This superior discrimination power for atherosclerosis that characterized apoB in our analysis may be attributed to the fact that apoB directly reflects the number of all atherogenic particles." (PMID 41374382, 2025). "In addition, we evaluated the oxidizability of those lipoproteins containing apoB to investigate the possible mechanisms of atherosclerosis." (PMID 39087075, 2024). "Likewise, progress in atherosclerosis vaccines has been promising at the preclinical level; however, studies on ApoB-specific T cells in humans remain scarce." (PMID 39766344, 2024). "Similarly, a review assessing associations of dietary patterns with atherosclerosis risk biomarkers (i.e., LDL-C, ApoB, and CRP) in FH patients, found beneficial effects of a healthy dietary pattern combined with an overall healthy lifestyle." (PMID 39525275, 2024). "Immunization with human ApoB reduced atherosclerosis significantly in Apoe−/− mice." (PMID 39161593, 2024). "Interestingly, epitopes from antigens of atherosclerosis, such as apolipoprotein B (ApoB) and LDL have similar immunological features with viral antigens, including CMV, HCV, and HPV." (PMID 38992867, 2024). "APOB is the most well studied and a clinically relevant atherosclerosis-related autoantigen." (PMID 38571941, 2024). "Reduced LSR expression is linked to the development of atherosclerosis in mice due to elevated levels of plasma non-HDL cholesterol as it affects apoB lipoprotein clearance." (PMID 38892018, 2024). "Experimental evidence suggests the cardioprotective role of APOB in enhancing survival and cardiac function post-MI, while numerous basic research studies have implicated PLTP in the development of atherosclerosis, with clinical studies broadly confirming its pro-atherogenic role as well." (PMID 39513871, 2024). "Perhaps in the progression of CHB disease, HBV reduces the risk of atherosclerosis through the incompletely verified molecular mechanism, resulting in a negative correlation between ApoB/ApoA1 ratio and the prevalence of HCC and LC." (PMID 38744926, 2024). "Finally, an emerging antigenic target of adaptive immunity during atherosclerosis includes ApoB, though current research has been skewed more towards T cell targeting of ApoB than B cell targeting." (PMID 39616399, 2024). "Additionally, both in murine atherosclerosis models and humans with cardiovascular disease, a population of apoB-specific T-helper cells was identified in experiments that used recombinant MHC." (PMID 39161593, 2024).
atherosclerosis (continued). "Previous large-scale studies on healthy individuals, including the UK Biobank, have shown correlations between IOP and the lipid indicators, such as TC, HDL-c, LDL-c, TG, ApoA, and ApoB, and the mechanism was thought to be involved with atherosclerosis or vascular." (PMID 39669501, 2024). "Thus, via LPL deficiency, impaired apoB-mediated lipoprotein clearance in the liver is eventually associated with high levels of VLDL and TG, both of which lead to atherosclerosis." (PMID 38892018, 2024). "Non-HDL is the sum of all cholesterol carried by apolipoprotein b – lipoprotein particles that can cause atherosclerosis." (PMID 37928909, 2023). "Moreover, resistin increases the synthesis of apolipoprotein B and thus accelerates the process of atherosclerosis by inducing dyslipidemia with high LDL, triglycerides and low HDL concentrations." (PMID 37048072, 2023). "Apolipoprotein B has been postulated as a key factor in the development of atherosclerosis, likely through the “response to retention” hypothesis." (PMID 37941911, 2023). "In addition to monocytes, T-lymphocytes also play an important role in the development of atherosclerosis, as they are activated by antigens such as oxLDL, apolipoprotein B (ApoB), and heat shock protein (HSP) presented by antigen-presenting cells (APCs)." (PMID 37998729, 2023). "Therefore, our article aims to focus on presenting the latest evidence that supports the significance of two particular molecules, interleukin 6 (IL-6) and apolipoprotein B (apoB), as potential biomarkers for atherosclerosis." (PMID 37629496, 2023). "The size and composition of apolipoprotein B particles, as well as the number of particles present in the bloodstream, would influence the tendency to be trapped in the arterial wall and contribute to the development of atherosclerosis." (PMID 37941911, 2023). "Much evidence suggests that atherosclerosis is initiated by flow disturbance-stimulated endothelial activation, followed by subendothelial apolipoprotein B (apoB) retention, monocyte-derived macrophage entry, smooth muscle cell (SMC) proliferation, and plaque formation." (PMID 37833942, 2023). "PCSK9 (proprotein convertase subtilisin/kexin type 9), HSP65, and ApoB are some of the possible antigens that may be used as atherosclerosis vaccine antigens." (PMID 37373933, 2023). "Therefore, personalised exercise can significantly reduce ApoB/ApoAI ratios and disrupt the balance between potential atherosclerosis and anti-atherosclerotic lipoprotein cholesterol particles." (PMID 37398909, 2023). "Activation of MAPK may affect apolipoprotein B stability and/or degradation, providing a potential target for AS-IV against atherosclerosis and hepatic steatosis." (PMID 35264962, 2022). "Similar to APOB and CD36, the CALM1, CALM2, and CALM3 encoding calmodulin 1, 2, and 3, respectively were differentially expressed and downregulated on the lipid and atherosclerosis pathway." (PMID 36506940, 2022). "It is well-known that apolipoprotein B (apo B)-containing lipoproteins transport cholesterol and other lipids throughout the body and play a central role in the initiation and progression of atherosclerosis." (PMID 35956420, 2022). "Studies have shown that induction of protective immunity with LDL or ApoB peptides in animal models could prevent atherosclerosis." (PMID 36703734, 2022). "In addition to an autoreactive T cell response, autoantibodies recognizing LDL, oxLDL, and ApoB have been detected in the plasma of mice and humans with atherosclerosis." (PMID 35479271, 2022). "Apolipoprotein B (APOB) is associated with dyslipidemia and atherosclerosis development." (PMID 36061816, 2022). "An increasing number of epidemiologic, genetic, and genome‐wide association studies suggest that reducing plasma ANGPTL3 levels by inhibiting hepatic ANGPTL3 synthesis will benefit apolipoprotein B levels and improve the metabolic measurements related to dyslipidemia and atherosclerosis." (PMID 35712827, 2022).
atherosclerosis (continued). "The first self-antigen proposed to be involved in this process was ApoB, suggesting the possibility that atherosclerosis could be the consequence of an auto-immune response." (PMID 35966516, 2022). "Adjusting the model for age, sex, LDL-C and ApoB levels demonstrated that the association of LDL-TG with atherosclerosis was independent of these well-known factors." (PMID 36684605, 2022). "Likewise, TG is a proxy for the concentration and composition of TG-rich lipoproteins (TRLs), which promote atherosclerosis via several mechanisms, including deposition of cholesterol and apoB in atherosclerotic lesions." (PMID 32907989, 2021). "Several self-antigens, native LDL, oxidized LDL, and the major component of LDL, such as apolipoprotein B (ApoB), could provoke autoimmune responses in atherosclerotic lesions and be involved in the pathogenesis of atherosclerosis." (PMID 34945203, 2021). "Through mechanisms that are not fully understood, high levels of apolipoprotein-B (Apo-B), correlated with high low-density lipoprotein (LDL) levels, are the major reasons causing vascular disease (atherosclerosis), leading to life-threatening complications, such as heart disease and stroke." (PMID 34711013, 2021). "Herein, we sought to evaluate whether Aire affects generation and activation of atherosclerosis-relevant ApoB+ T cells in Apoe−/− mice." (PMID 35097028, 2021). "Hypothyroidism is well understood to increase serum lipid levels—such as total cholesterol, LDL cholesterol, and apolipoprotein B—which are the main mechanism in the development of atherosclerosis plaque, whereas recent studies also explore the role of hyperthyroidism in vascular atherosclerosis." (PMID 34987480, 2021). "Furthermore, it is known that LDL-derived ApoB-peptides elicit antigen-specific responses and drive T cell activation and formation of memory pools in mouse and human atherosclerosis." (PMID 35087883, 2021). "Vaccination with tolerogenic adjuvants and immunogenic ApoB-peptides may therefore have the potential to reinforce the protective limb of ApoB-specific immunity even in patients with established atherosclerosis." (PMID 33669769, 2021). "As retention of apoB in the walls of arteries can initiate inflammation leading to atherosclerosis development, a decrease in LDL-C levels may lead to a reduction of the risk of cardiovascular events." (PMID 34351937, 2021). "In this comprehensive analysis of >220 serum biomarkers in patients with JSLE who mostly had normal total cholesterol and triglyceride levels, apoB:apoA1 was also identified as a marker correlating with elevated metabolites in adult patients of SLE with atherosclerosis." (PMID 33774330, 2021). "However, the Atherosclerosis Risk in Communities (ARIC) study of 9026 American populations reported the null effects of ApoB and ApoB/A1 ratio on diabetes." (PMID 33794863, 2021). "To test this hypothesis, we checked if the ratio between LDL (or apolipoprotein B (ApoB)) and HMW adiponectin concentrations are associated with the initial stages of atherosclerosis in humans." (PMID 34680515, 2021). "Moreover, immunization against the ApoB-peptide p6 was atheroprotective in 8-week old Apoe−/− mice, but enhanced atherosclerosis in 13-week old Apoe−/− mice pre-fed a WD for 5 weeks." (PMID 33266027, 2020). "The 35% reduction in flow of apoB down the delipidation cascade will have predictable consequences for the products of lipolysis of VLDL1 — remnant VLDL particles and LDL — which are implicated as causal factors in atherosclerosis." (PMID 33170809, 2020). "Although tetramers containing the newly identified MHCII-restricted epitopes in ApoB have recently been used to detect antigen-specific T cells in atherosclerosis development, safe translation of these approaches to the clinical setting awaits thorough investigation." (PMID 32849502, 2020).